INS (insulin)
Diseases named in the same sentence as INS in open-access papers (continued):
Sharing a sentence is not in itself a finding about the gene and the disease.
Obesity (continued). "Patients with obesity have been shown to have epigenetic alterations associated with CpG methylation and the expression pattern of miRNAs at all stages of adipocyte differentiation, affecting their lipid metabolism and insulin sensitivity in adipose tissue and causing β-cell dysfunction." (PMID 36839169, 2023). "Obesity induced by increased energy uptake and low physical activity is often associated with enlarged, hypertrophic white adipocytes that fail to adequately store the excess fat, leading to lipid spillover and ectopic accumulation in other tissues and decreasing insulin sensitivity." (PMID 36768391, 2023). "However, central obesity may have more influence on cancer risk than overall obesity because metabolic derangement is reflected by insulin and IGF levels." (PMID 36937438, 2023). "Factors associated with poor glycemic control were obesity [odds ratio (OR)=1.9], DM duration between 5 and 10 years or more than 10 years (OR=1.8 and 2.5, respectively), and the use of a combination of oral hypoglycemic agent plus insulin or insulin alone (OR=2.4 and 6.2, respectively)." (PMID 37008178, 2023). "We also identified suggestive associations in several obesity genes; while these associations warrant further replication and functional investigation, they contrast with findings from adult-onset T2D association studies that skew much more to genes involved in insulin secretion." (PMID 37292813, 2023). "It mainly causes changes in some metabolic pathways, such as amino acid, insulin, and bile metabolism, in addition to altering the biosynthesis and degradation of some secondary metabolites, which are mostly positively associated with obesity and lipid metabolism." (PMID 36655078, 2023). "In addition, we also reported that coffee decoction possesses the ability to suppress insulin-caused adipocyte differentiation, suggesting that coffee may also be effective in the prevention of obesity." (PMID 38203488, 2023). "Moreover, it could be a valuable tool in women with prior endometrial cancer and obesity to reduce body weight, visceral adipose tissue, circulating insulin levels and risk of recurrence." (PMID 37405618, 2023). "Finally, uric acid could be useful to identify children with obesity at higher risk of delayed insulin response, OS and inflammasome activation." (PMID 37599368, 2023). "Furthermore, obesity is linked to a deficiency of macronutrients (i.e., proteins) and primarily micronutrients such as minerals, vitamins, and related hormones (i.e., leptin, insulin, and ghrelin) that play pivotal roles in obesity-associated comorbidities." (PMID 37686839, 2023). "High-protein intake during infancy may increase weight gain and obesity risk in later years and observational studies have found an increased risk for the development of NCDs, because of the elevated levels of insulin and of insulin-like growth factor-1 (IGF-1)." (PMID 38201860, 2023). "Interestingly, a gene–environment interaction has been described between rs1801282 SNP and nutrition, where BMI and insulin concentration are inversely associated with the polyunsaturated to saturated fatty acids ratio of the diet in carriers of the obesity G risk allele." (PMID 36986146, 2023). "Similarly, in another study, mice with a heterozygous deletion of ADAM17 were protected from obesity (by elevating their energy expenditure in response to high-fat diet) and its associated metabolic dysregulation, such as glucose intolerance and insulin insensitivity." (PMID 37121509, 2023). "However, while all methods of weight loss provide health benefits and reduce the risk of obesity-related comorbidities, exercise additionally improves cardiovascular and metabolic health and additional improvements in markers related to insulin signaling." (PMID 40880838, 2023).
Obesity (continued). "Resistance to the cellular effects of insulin is a significant contributor to obesity and gradually leads to a failure of pancreatic β-cell function, which inevitably results in impaired insulin secretion due to a progressive loss of insulin sensitivity of peripheral target tissues." (PMID 38260166, 2023). "Visceral adipose tissue is also resistant to insulin and leptin and is the site of altered secretion of molecules and hormones such as adiponectin, leptin, resistin, tumor necrosis factor and interleukin-6, which exacerbate cardiovascular disease associated with obesity." (PMID 37081416, 2023). "Establishing a ~1400 prioritized obesity-associated gene set, we performed protein-protein interaction analysis and identified 74 key genes enriched in biological pathways regulating feeding behavior, energy expenditure, metabolic homeostasis, and insulin secretion." (PMID 37620670, 2023). "Adiponectin, an adipokine, enhances insulin sensitivity and promotes anti-inflammatory and antifibrotic activities; however, studies show that adiponectin is reduced in patients with obesity and coronary artery disease, suggesting its crucial role in obesity-associated cardiovascular diseases." (PMID 36901009, 2023). "In OGDM‐Insulin, faster changes in weight z‐score could have important clinical implications if those persist after 60 months of age and translate into higher overweight and obesity risk later in childhood." (PMID 37597238, 2023). "In addition, obesity can induce genetic mutation/epigenetic modification due to the presence of a high amount of fat tissues that causes a metabolic imbalance of circulating levels of insulin." (PMID 37512149, 2023). "In fact, maternal HFD during gestation and lactation seems to have a negative impact on offspring generation and may increase the propensity to impaired glucose tolerance and insulin sensitivity, as well as the predisposition to obesity development later in the offspring’s life." (PMID 35409278, 2022). "The aim of this study is to assess with the same study population, by comparing groups with low vs high obesity risk (LR vs HR), whether alterations in BGU, insulin action in the brain–liver axis and whole-body insulin sensitivity occur already in pre-obese state with risk factors for obesity." (PMID 36288097, 2022). "Consequently, taurine supplementation results in increased body temperature, reduced body weight or body weight gain in obesity models, alleviated high-fat diet (HFD)-induced obesity, improvement in the lipid profile, metabolic risk factors and insulin sensitivity." (PMID 35954180, 2022). "Until now, the results of the present work have shown that molecules associated with the insulin and adiponectin signaling pathways are decreased in women with obesity independently of the PCOS condition; moreover, these levels could be re-established with MTF treatment." (PMID 35409282, 2022). "A prevalent hypothesis has proposed that exercise may reduce the risk of cancer through an exercise-dependent regulation of common cancer risk factors, including sex hormones, insulin, insulin-like growth factor-1, and pro-inflammatory cytokines, which are all associated with obesity and adiposity." (PMID 35361802, 2022). "However, insulin per se can also cause obesity due to its nature as a potently anabolic hormone." (PMID 36292657, 2022). "Several other factors and mechanisms triggered by obesity may be implicated in tumor development and progression, such as modulations in sex steroids, insulin and insulin resistance, altered secretion of adipokines, and the activation of insulin-like growth factor (IGF) pathways." (PMID 36401194, 2022). "Thus, we speculated that, relative to the sharp weight loss, the recovery of obesity-induced compensatory pancreatic β cell proliferation may have been delayed, leading to a severe improper postprandial secretion of insulin after surgery for HMO-I." (PMID 36407309, 2022).
Obesity (continued). "These patients might be expected to have a better response to therapeutic strategies than those presenting a “metabolically unhealthy obesity phenotype”, where genetic, transcriptional, and environmental factors associated with adipose tissue homeostasis and insulin sensitivity are involved." (PMID 36261843, 2022). "Interestingly, adjustment for improvement of different estimates of obesity during weight loss indicated that additional mechanisms apart from changes in body weight appear to play a relevant role for improvement of insulin sensitivity during weight loss in MUO." (PMID 35346256, 2022). "Therefore, the hyper-methylation of SOCS3 in the gene promoter and its nearby region silences the inhibitory effect on leptin and insulin of SOCS3, whereas hyper-methylation in the gene body facilitates it to inhibit the activity of insulin and leptin, resulting in a high risk of obesity." (PMID 36145200, 2022). "Some authors have suggested that obesity itself might be a determining factor in muscle mass loss, because of metabolic disorders associated with this disease, such as insulin resistance, systemic oxidative stress mainly affecting skeletal muscle mass, and inflammation." (PMID 36558390, 2022). "Interestingly, Treg-specific loss of IL-10 resulted in increased insulin sensitivity and reduced obesity in high-fat diet-fed male mice, suggesting that Tregs may promote healthy obesity in some settings." (PMID 35039633, 2022). "The mechanism or mechanisms responsible for the increase in insulin secretion caused by obesity are unclear, but probably involve an increase in both β cell numbers and the function of individual β cells, which together increase the insulin secretory response to a glucose stimulus." (PMID 34905513, 2022). "They found that higher insulin demand, especially at breakfast and dinner, was associated with being overweight, and night eating may be associated with eating compulsive behaviors related to obesity." (PMID 35745274, 2022). "This trend became more remarkable in obese II for these four diseases, indicating that obesity is associated with a higher mortality than normal BMI because it disturbs hemostasis via physiological mechanisms, such as increased inflammation and insulin resistance." (PMID 36344547, 2022). "Furthermore, leptin and insulin influence risk of pre-eclampsia independently of obesity." (PMID 35104295, 2022). "The reason for this inverse relationship between NT-proBNP and HbA1c reported here and in other population-based studies, is unclear but may directly involve insulin resistance, adipose tissue cytokine overexpression and obesity-linked neurohormonal dysregulation." (PMID 36216842, 2022). "Unsurprisingly, IL-1RA knockout mice are resistant to HFD-induced obesity and show enhanced insulin sensitivity due to increased energy expenditure, suggesting that increased serum IL-1RA levels might contribute to the pathogenesis of obesity and associated metabolic abnormalities." (PMID 35909571, 2022). "We also showed that, independently from obesity, combined IR-dyslipidemia underlies atherogenic (worsened aortic atherosclerosis) and deleterious cardiovascular effects (decreased cardiac contractility and reduced insulin-mediated vasorelaxation) and induces gut microbiota dysbiosis." (PMID 35196347, 2022). "Regarding insulin, a recent study has found that the triglyceride and glucose index (TyG) correlates with the severity and mortality of COVID-19 patients, which builds upon epidemiological observations identifying obesity as a risk factor among COVID-19-related fatalities." (PMID 35102208, 2022). "Altered maternal levels of metabolic substrates and hormones in obesity contribute to maternal insulin resistance, oxidative stress and inflammation, resulting in perturbations in glucose and lipid homeostasis and feeding circuitry in the perinatal period, contributing to long-term obesity risk." (PMID 36329895, 2022).
Obesity (continued). "In this case, MTF could enhance the insulin-sensitizing effect of adiponectin and/or decrease the levels of molecules related to the TNFα signaling pathway and therefore diminish the insulin-repressor effect of this pro-inflammatory cytokine associated with obesity." (PMID 35409282, 2022). "Obesity and metabolic disorders are associated with increased blood bacterial lipopolysaccharide (LPS) level and its initiated low-grade of inflammation, and activation of the deacetylase Sirtuin 1 restored insulin sensitivity in tissues with insulin resistance." (PMID 35074429, 2022). "Moreover, high salt intake prevented obesity development during high-fat-diet exposure in both male and female mice, although it did not prevent the emergence of fat-induced metabolic dysfunction typified by glucose intolerance and loss of insulin sensitivity." (PMID 36613742, 2022). "In addition to an increase in intestinal polyp formation in the ApcMin mice, exposure to a HFD increases systemic and local inflammation before the onset of obesity, as well as metabolic syndrome-associated characteristics, including an elevated level of insulin or glucose." (PMID 35563777, 2022). "Obesity has a very heterogeneous origin, and high rates observed in our series could be related with some features of the syndrome (e.g. thyroid disorders), but the association of PTEN and obesity could also be related with the involvement of PTEN in the insulin pathway." (PMID 35227301, 2022). "In addition, obesity may very well cause insulin resistance through promoting chronic inflammation in adipose tissue, and by increasing insulin secretion in the system, thereby activating multiple growth pathways." (PMID 36292657, 2022). "Persistent in vitro and in vivo exposure of macrophages to insulin, which could occur in chronic hyperinsulinemia (a condition associated with obesity and the metabolic syndrome), renders them insulin resistant and produces an M2 phenotype that is less responsive to stimuli." (PMID 35406000, 2022). "IF seems to modulate inflammatory pathways in the brain, which may also be correlated with the brain-microbiota axis, improving hypothalamic signaling of leptin and insulin, and inducing the autophagic pathway in hypothalamic neurons, contributing to weight loss in obesity." (PMID 35445066, 2022). "This may be one link to the known association between phthalate exposure and obesity risk given that beta oxidation is involved in numerous obesity-related physiological processes, including lipid metabolism, hepatic fat accrual, and glucose-insulin homeostasis." (PMID 36040907, 2022). "Excessive GPX1 activity may be detrimental to T2D and obesity, as demonstrated by the positive association between the overexpression of GPx1 and the impaired glucose clearance, hyperinsulinemia, hyperglycemia, and reduced insulin signaling in a mouse model." (PMID 35740085, 2022). "Thus, apart from an adjusted body mass index (BMI) in diagnosing obesity in children 2 years and older, it still remains unclear when to screen for metabolic complications and assessing (ab)normal insulin sensitivity during childhood." (PMID 34742239, 2021). "Increased carbohydrate intake, in particular refined carbohydrates and sugars, have been linked to obesity and T2D, and the use of restricted carbohydrate diets have shown to be effective in reducing body weight and WC, as well as, fasting glucose, HbA1c, and plasma insulin levels." (PMID 33498618, 2021). "Obesity is associated with low-grade inflammation and metabolic syndrome, which is characterized by alterations in glucose, fatty acids, and amino acid metabolism and leads both to a decrease in insulin sensitivity and a decline in one’s ability to adjust to energy availability." (PMID 34208508, 2021).
Obesity (continued). "The βOHB and SCFAs can influence epigenetic changes in infant obese gene expression and exert potential anti-obesity and anti-inflammatory effects by targeting obesity-associated inflammation via interactions of the hypothalamic appetite-regulating hormones leptin and insulin." (PMID 34835958, 2021). "Also, decreased insulin secretion due to the defect of the β-cell in the pancreas could explain the association between obesity and insulin resistance." (PMID 33986312, 2021). "Increased plasma LPN can transduce signals to obesity gene receptors in the hypothalamus to inhibit neuropeptide Y gene expression to cause food intake reduction and energy consumption and inhibit islet β-cells to secrete insulin, which feeds back to decrease LPN production." (PMID 33570444, 2021). "The therapeutic mechanisms underpinning these improvements are poorly understood based upon the available studies, though the theoretical advantage to these medications may predominantly be weight loss in the setting of overweight/obesity, which may improve insulin sensitivity." (PMID 33828529, 2021). "After selection and assignment of adolescents into groups, defined based on BMI, insulin secretory patterns and glucose tolerance, the present study revealed clusters of metabolites associated either with insulin response (hyperinsulinaemia/IR), or with obesity." (PMID 33438144, 2021). "The relative sparing of the MAP-K insulin pathway in obesity-related IR may help to explain the known association between obesity and malignancy and promotes IR and the harmful effects of compensatory hyperinsulinaemia as central to the pathogenesis of such tumours." (PMID 33430419, 2021). "Thus, in obesity and MetS, hypothalamic inflammation may cause resistance to the anorexigenic hormones leptin and insulin, leading to the defective regulation of food intake and energy expenditure." (PMID 33557413, 2021). "Besides the increased pro-inflammatory markers, obesity is often associated with a decrease in adiponectin, an anti-inflammatory adipokine deemed beneficial against dyslipidemia and important in maintaining glucose and insulin homeostasis." (PMID 34436472, 2021). "The pathophysiology behind an increased risk of kidney disease in obesity is not completely understood, but factors such as peripheral insulin resistance, pro-inflammatory state, glomerular hyperfiltration, and dyslipidemia could increase the risk for AKI during illness." (PMID 34970220, 2021). "Indeed, a Mendelian randomization analysis showed a positive association between genetically predicted fasting insulin with breast cancer risk and suggest that genetically determined obesity and insulin-related traits play an important role in the etiology of breast cancer." (PMID 33495474, 2021). "Assuming that decreased insulin sensitivity plays a substantial role in the association between obesity and kidney disease, we hypothesized that the TyG index is associated with risk of ESKD and that part of the association between BMI and ESKD is mediated through the TyG index." (PMID 33787913, 2021). "Although the underlying biochemical mechanisms are not clearly defined, some researchers suggest that obesity-related metabolic abnormalities, such as long-term chronic inflammation, insulin resistance or some adipokines, may contribute to the positive correlation between TC risk and obesity." (PMID 33801171, 2021). "Furthermore, many studies have demonstrated an association between high adiponectin levels and increased insulin sensitivity, β cell function, and survival, whereas obesity and elevation of inflammatory CKs in AT have been linked to reduced adiponectin production." (PMID 33539327, 2021). "Interestingly, these animals (35–39 weeks of age) presented lower amino acid levels than that of mice fed with SCD, which might have been caused by high insulin levels and impaired glucose tolerance in aging and diet-induced obesity (DIO) mice." (PMID 34002801, 2021).